IL6 (interleukin 6)
Diseases named in the same sentence as IL6 in open-access papers (continued):
Sharing a sentence is not in itself a finding about the gene and the disease.
breast cancer (continued). "IL-6 has been found to stimulate STAT3 in breast cancer-derived MDSCs, and the unregulated expression of IDO was through the activation of STAT3 and NF-κB pathway." (PMID 30998767, 2019). "Elevated inflammatory markers such as CRP, neutrophil to lymphocyte ratio, interleukin-6, have been related to poorer survival amongst breast cancer patients." (PMID 31262969, 2019). "The mean serum concentration of IL-6 was observed as 31.7 pg/mL in patients with breast cancer and 3.3 pg/mL in the normal cohort." (PMID 31766574, 2019). "In the present study, we indicated that PIM1 was transcriptional activated by IL-6/STAT3 axis and was critical for IL-6 induced breast cancer cell EMT and stemness." (PMID 30989585, 2019). "Lastly, a recent study demonstrated that hypoxia-induced secretion of IL6 specifically by ERα+ breast cancer cells was capable of elevating both ERα+ and ERα− bCSC self-renewal and proliferation in a JAK-STAT pathway-dependent manner in vitro." (PMID 31450577, 2019). "The breast cancer cell lines, co-cultured with all types of adipose cells, show an overexpression of pro-inflammatory cytokines: IL-6, IL-8, IP-10, CCL2 and CCL5." (PMID 31661891, 2019). "Constitutive IL-6 expression in breast cancer cells maintains their EMT phenotype, which has been implicated in the generation of a CSC phenotype." (PMID 31417869, 2019). "Reduction in FOXA1 expression contributes to cancer stem cell-like properties in Tamoxifen-resistant breast cancer cells through induction of Interleukin-6 (IL-6)." (PMID 30819139, 2019). "MTF efficiently decreases Vimentin, SNAIL and cell proliferation in mesenchymal breast cancer cells and also reverses IL-6-induced EMT by blocking STAT3 and NF-κB phosphorylation." (PMID 31337349, 2019). "Overexpression of CRYβB2 increased IL6 production, upregulated the expression of proliferative genes, and increased proliferation of breast cancer cells in vitro and in vivo." (PMID 31511085, 2019). "In this study, we reveal a novel finding which demonstrates that high expression of OSM and IL-6 in breast cancer tumors are correlated with reduced breast cancer patient survival." (PMID 31007849, 2019). "Further, IL-6 has been proved as the transcriptional target of YAP involved in basal-like breast cancer." (PMID 31299894, 2019). "IL-6 treated primary human mammospheres and human breast cancer cells grown in suspension (three-dimensions) produces multicellular spheroid structures containing stem/progenitor cells dependent on Notch-3 signaling." (PMID 31557902, 2019). "It is well-documented that high expression levels of IL-6 in DCs are responsible for defects in migration in other types of cancers including, cervical cancer, breast cancer, and ovarian cancer." (PMID 31164886, 2019). "Its role in breast cancer growth and bone metastasis was confirmed by evaluating blood samples from healthy, breast cancer, or metastatic breast cancer patients, where the higher levels of IL-6 were detected in patients with metastatic bone disease." (PMID 31847214, 2019). "Previous research in breast cancer indicated that IL‐10 and IL‐6 inhibit DC maturation through repression of miR‐155 upregulation." (PMID 30628173, 2019). "RANKL and IL-6 mediate direct paracrine/autocrine signaling between cells of the osteoblast lineage and cancer cells, enhancing the growth of metastatic breast cancers within bone." (PMID 31847214, 2019). "While serum IL-6 levels have previously been demonstrated to be correlated with breast cancer development and reduced survival, this is the first study investigating OSM." (PMID 31007849, 2019). "More importantly, E2 and IL-6 can synergistically promote the healing of breast cancer cells scratch and migration." (PMID 31409371, 2019). "It has been reported that adipocyte-derived IL-6 promoted the up-regulation of PLOD2 in breast cancer cells via activating JAK/STAT3 and PI3K/AKT pathways." (PMID 31170987, 2019).
breast cancer (continued). "In breast cancer cells, IL-6 dramatically induced the expression of TWIST1 and SNAIL1 via STAT3 activation, leading to the initiation of an EMT." (PMID 31123345, 2019). "Our data demonstrate that OSM and IL-6 expression levels correlate in the breast tumor microenvironment, breast cancer patient serum, and in in vivo mouse studies." (PMID 31007849, 2019). "When Notch, Wnt and transforming growth factor-β (TGF-β) signaling pathways are activated, IL-6 also regulates self-renewal of breast cancer CSCs and promotes the survival and proliferation of CSCs." (PMID 31500658, 2019). "Our previous results suggested that osteoblasts are significantly altered in the presence of breast cancer cells to increase osteoblast production of IL-6, IL-8, VEGF, MCP-1, and GRO-alpha in late-stage disease." (PMID 30813947, 2019). "IL-6, a critical cytokine for MM survival, was previously shown to be secreted by MDSCs in breast cancer." (PMID 30979371, 2019). "It was shown that the activation of an IL-6/STAT3/PTEN/NF-κB inflammatory feedback loop mediates trastuzumab resistance in HER+ breast cancer cells by expanding the CSC population." (PMID 31557902, 2019). "We recently reported that human adipocytes induced EMT occur via the IL-6/STAT3 axis in breast cancer cells." (PMID 31383893, 2019). "In summary, our findings provided insight into the mechanism by which pro-inflammatory cytokine IL-6 induced breast cancer cell EMT and stemness and provided the potential approach to suppress the upregulation of PIM1 by IL-6." (PMID 30989585, 2019). "When adipocytes are co-cultured with breast cancer cells, the expression and secretion of IL-6 in adipocytes increase, promoting the invasion and migration of cancer cells." (PMID 31500658, 2019). "It has been described that melatonin, in co-cultures of human breast cancer cells and 3T3-L1 fibroblasts, decreases the levels of TNFα, IL-11, and IL-6 in the culture media and downregulates TNFα, IL-11, and IL-6 mRNA expression in both types of cells." (PMID 31412584, 2019). "Collectively, these results suggest that OSM, IL-6, and IL-1β are interrelated in breast cancer patient metastasis and survival." (PMID 31007849, 2019). "We recently identified IL6 as the only down-regulated cytokine in breast cancer samples using cytokine assays." (PMID 31429720, 2019). "Among these, polymorphisms in TNFa, IL6, and IL1-b were associated with fatigue after breast cancer treatment completion." (PMID 31795208, 2019). "In malignant mammary tumors, Il-6 was significantly downregulated by treatment with TAM + JEKHT, compared with the TAM only group." (PMID 30640711, 2019). "We have demonstrated that OSM and IL-1β act synergistically in the production of IL-6 by breast cancer cells and in the potential exacerbation of inflammatory conditions." (PMID 31007849, 2019). "IL-6 levels are increased in serval types of cancers including breast cancer, liver cancer and lung cancer." (PMID 30989585, 2019). "Down-regulation of p300 levels by its siRNA attenuated IL-6-induced breast cancer cell migration about 60%." (PMID 31409371, 2019). "Based on these observations, we next examined the role of MMP2 and MMP9 in IL-6-induced breast cancer cell migration." (PMID 31409371, 2019). "Adipocytes play crucial roles in the proliferation, survival, and invasion of breast cancer cells via secreting cytokines (including leptin, adiponectin and IL-6) or providing energy (such as fatty acids)." (PMID 31170987, 2019). "Considering this information, we explored the effects of this drug on the proliferation and migration of breast cancer cells with an initial epithelial phenotype and that were transformed to a mesenchymal phenotype by the exposure to IL-6." (PMID 31337349, 2019). "The overexpression of IL-6 in MDA-MB-231 cells has been reported in many studies, but the implications of IL-6 expression in breast cancer are yet unclear." (PMID 31252615, 2019).
breast cancer (continued). "In conclusion, this study substantiates the rationale for a therapeutic design that simultaneously targets multiple cytokines, such as OSM, IL-6, and IL-1β, as these cytokines are strongly correlated with each other in breast cancer." (PMID 31007849, 2019). "MBCDF and MBCD17 primary epithelial breast cancer cells were treated with 40 ng/mL IL-6; after 24 h of IL-6 exposure, 10 mM MTF was added and cells were incubated for an additional 24 h period." (PMID 31337349, 2019). "In particular, STAT3, a transcription factor stimulated by IL-6, was shown to be consistently expressed in most breast cancer cells." (PMID 31252615, 2019). "MSCs in breast cancer regulate CSCs through cytokine loops involving IL-6 and CXCL-7, thereby accelerating tumor growth." (PMID 31417869, 2019). "Serum IL-6 levels are increased with advanced stages and related to poor survival in various cancers, and IL-6 drives breast cancer metastasis and stemness." (PMID 30885232, 2019). "Our data unambiguously attribute to bCAFs an anti-apoptotic effect on luminal breast cancer cells, which relies on paracrine and autocrine functions of IL-6." (PMID 30631150, 2019). "In another study involving multiple breast cancer subsets, IL-6 has been shown to increase cancer stem cell properties of tumor cells via EMT." (PMID 31075939, 2019). "IL-6, a multifunctional cytokine that was originally characterized as acting in immune and inflammatory responses, appears to play a key role in breast cancer growth and bone metastasis." (PMID 31847214, 2019). "As PIM1 was significantly upregulated by IL-6/STAT3 activation, we further investigated the roles of PIM1 in IL-6-induced breast cancer cell EMT and stemness." (PMID 30989585, 2019). "Our results indicate that there is a strong correlation between OSM and IL-6 expression and secretion levels in breast cancer." (PMID 31007849, 2019). "STAT3 can be phosphorylated by activated JAK2 induced by IL-6, which is a key mediator of the inflammatory response and functions as a crucial regulator in the progression of breast cancer." (PMID 31186039, 2019). "To understand the functional of p300, we also tested its role in IL-6-induced breast cancer cell migration and proliferation." (PMID 31409371, 2019). "ER- breast cancer has been correlated with increased NF-κB activity and increased expression of certain cytokines (IL-6, IL-8) and chemokines (CCL5, MCP-1 [CCL2])." (PMID 30736340, 2019). "Among these cytokines, interleukin-6 (IL-6) has been reported to promote breast cancer stem cells’ renewal, EMT and metastasis." (PMID 31766724, 2019). "Using female Balb/C mice and syngeneic mammary tumor cells (67NR, 4T1, 4T07), the authors demonstrated that peripheral tumor growth promotes systemic inflammation, largely driven by interleukin-6 (IL-6)." (PMID 31174326, 2019). "Remarkably, COX-2 has been shown to promote metastatic potential of breast cancer cells in TAMs, while IL-6 signaling is assumed to contribute to a pro-tumor condition by supporting angiogenesis and tumor elusion of immune surveillance." (PMID 31540502, 2019). "Higher concentrations of many inflammatory markers, including CRP, IL-1β, IL-6, and TNF-a, have been linked with a higher risk of breast cancer through the stimulation of angiogenesis, proliferation, migration, metastasis, and prevention of apoptosis." (PMID 31430979, 2019). "In particular, the literature suggests the use of IL-6 as a prognostic marker for breast cancer metastasis and survival." (PMID 31007849, 2019). "Our follow up studies using human patient serum demonstrated that high levels of OSM and IL-6 were detected in the serum of breast cancer patients compared to normal healthy volunteers." (PMID 31007849, 2019). "Using the Curtis TCGATM dataset, we have determined that there is a correlation between expression levels of OSM, IL-6, and IL-1β and reduced breast cancer patient survival (r = 0.6, p = 2.2 x 10−23)." (PMID 31007849, 2019).
breast cancer (continued). "Transwell assay was used to detect the invading ability of breast cancer cells induced by IL-6 or PIM1." (PMID 30989585, 2019). "Signal transducer and activator of transcription 3 (STAT3) is selectively activated by IL-6 and thought to be constitutively expressed in more than 50% of breast cancers." (PMID 31252615, 2019). "Recently, STAT3/IL6 was reported to mediate signalings endowing breast cancer cells with stem-like properties." (PMID 31709178, 2019). "Alternatively, it was determined that IL-6 is produced by CSCs in multiple myeloma, breast cancer, and Squamous cell carcinoma with a relatively significant concentration rather than other cancer cells." (PMID 31024835, 2019). "IL-6 also seems to enhance the ability of breast cancer cells (tumor self-seeding) to survive, seed, and colonize distant sites, thereby contributing to tumor progression and metastasis." (PMID 31557902, 2019). "A similar result was also reported that breast cancer cell line-derived exosome stimulates the NF-kB pathway in macrophages, which leads to the secretion of pro-inflammatory factors such as IL-6, TNF-α, GCSF, and CCL2." (PMID 31686989, 2019). "Interleukin (IL)-6 plays a crucial role in the progression, invasion, and metastasis of breast cancer." (PMID 31252615, 2019). "Of note, our prior data using advanced bone metastatic breast cancer mouse models suggest that increased osteoblast-derived expression of IL-6, among other proteins, drives metastatic progression in the bone." (PMID 30813947, 2019). "In breast cancer, IL-6 on tumor cells has been shown to induce EMT by repressing E-CADHERIN via STAT3 activation." (PMID 31075939, 2019). "In this study, we aimed to determine the role of the IL-6/pSTAT3/HIC1 axis in the breast cancer microenvironment, including in cancer-associated fibroblasts (CAFs) and breast cancer cells." (PMID 31795965, 2019). "Increased levels of IL-6 were also highlighted in sera of mice with bone metastases, and by using a humanized 3D breast cancer bone metastasis model in which the higher levels of IL-6 were found in the presence of an osteoporotic microenvironment." (PMID 31847214, 2019). "In breast cancer, the secretion of adipocyte-derived IL-6 is regulated by interaction with tumor cells." (PMID 31170987, 2019). "In the present study, we investigated the role of IL-6 in human breast cancer cell line MDA-MB-231 in terms of tumor growth and metastasis and elucidated the molecular mechanism underlying IL-6-mediated inflammation in cancer metastasis." (PMID 31252615, 2019). "The contents of β-ABA exhibited the highest average correlation to inhibition of TNF-α, IL-6, and IL-8 cytokine release as well as cytotoxicity against breast cancer cells." (PMID 31581678, 2019). "The inhibitory effect of ODZ10117 on tyrosine-phosphorylated STAT3 was greater than the known inhibitors in breast cancer cells that are persistently activated or activated by IL-6-stimulation." (PMID 31684051, 2019). "Other studies have also reported the presence of cytokine co-expression such as tumor necrosis factor alpha (TNFα) expression with IL-6 to have a prognostic significance in breast cancer." (PMID 31007849, 2019). "When IL-6R is blocked by anti-IL-6R antibody, the metastasis of breast cancer induced by IL-6 is reversed." (PMID 31500658, 2019). "Accordingly, co-injecting human or mouse MSCs with IRISOE TNBC tumor cells promoted the formation of aggressive mammary tumors, high circulating IL-6 and PGE2 levels, and reduced overall survival." (PMID 31014367, 2019). "Beyond the set of genes identified by this study, ZEB1 has also been shown to directly regulate the expression of IL-6 and other cytokines by breast cancer cells to promote accumulation of myeloid-derived suppressor cells in a mouse model of breast cancer." (PMID 31780722, 2019). "IL6 is found to be widely involved in several tumors, including PCa, breast cancer, lung cancer, and melanoma." (PMID 31555577, 2019).
breast cancer (continued). "IL-6 regulates the tumor microenvironment, the generation of breast cancer stem cells, and metastasis through the downregulation of E-cadherin." (PMID 30791501, 2019). "The plasma level of IL-6 is much higher in patients with breast cancer than in healthy donors and correlates with frequent metastasis and poor survival in breast cancer." (PMID 31252615, 2019). "IL-6 is overexpressed in multiple cancers including breast cancer and high expression levels correlate with poor clinical outcomes in cancer patients." (PMID 31075939, 2019). "In HER2-positive breast cancer, IL-6 can also induce the production and maintenance of breast cancer stem cells (CSCs) through nuclear factor kappa-B (NF-κB) and STAT3 signaling pathways, then promoting tumor progression." (PMID 31500658, 2019). "Further analysis of the breast cancer cDNA arrays (n = 124) confirmed positive correlations of MCT-1 expression with that of IL-6 (r = 0.48, p < 0.001) and IL-6R (r = 0.27, p = 0.002)." (PMID 30885232, 2019). "The results confirmed that TNF-α induces upregulation of CCL2 expression in both breast cancer cell lines and IL-6 expression in MDA-MB-231 cells." (PMID 31665136, 2019). "MBCDF and MBCD17 breast cancer cells were treated with IL-6 and MTF alone or in combination and cell proliferation was assessed by MTT assay at 0, 1, 3 and 5 days of stimulation." (PMID 31337349, 2019). "In vitro, over-expression IL6 induces genes involved in epithelial-mesenchymal transition and lowers E-cadherin, supporting that IL6 can regulate adhesion and migration of breast cancer cells." (PMID 31398937, 2019). "Analysis of IL-6 expression levels by western blot in breast cancer cells after culturing in adipocyte CM for 48 hours followed by treatment with niclosamide shows a steady decrease in IL-6 levels at regular time levels." (PMID 31383893, 2019). "In this study, we investigate the effect of OSM, IL-6, and IL-1β on breast cancer patient survival as well as how these cytokines are interrelated in terms of cell signaling." (PMID 31007849, 2019). "This study aimed to explore the effect of dietary magnesium intake on breast cancer risk both directly and indirectly via its effect on inflammatory markers C-reactive protein (CRP) and interleukin-6 (IL-6)." (PMID 30962499, 2019). "Breast cancer cells treated with 1 mM AICAR alone or added 2 h before IL-6 were collected for protein extraction 2 days after treatment." (PMID 31337349, 2019). "These transcription factors, which regulate expression of Vimentin and SNAIL, increased in cultured primary breast cancer cells in response to IL-6." (PMID 31337349, 2019). "Some cytokines (IL-1, IL-6, IL-11, TGFβ) stimulate, while others (IL-12, IL-18, IFNs) inhibit breast cancer proliferation and/or invasion." (PMID 31557971, 2019). "In the present study, we analyzed the effects of MTF on the mesenchymal phenotype and IL-6-induced EMT in cultured primary breast cancer cells." (PMID 31337349, 2019). "In breast cancer, head and neck squamous cell carcinoma, gastric cancer, and glioma, IL-6 promotes stem cell self-renewal through the classical IL-6R/gp130/STAT3 signaling pathway." (PMID 29770167, 2018). "Paradoxically, cytotoxic chemotherapy further initiates TAM recruitment into invasive carcinoma, where coculture with breast cancer cells results in high IL-6 levels leading to the activation of cancer stem cells." (PMID 30103404, 2018). "Here, we showed that GRAMD1B expression is upregulated on IL-6 but downregulated upon treatment with the JAK2 inhibitor AG490 in the breast cancer MDA-MB-231 cells." (PMID 29934528, 2018). "In the xenograft tumor model of breast cancer, ectopic expression of IL-6 can significantly increase the infiltration of Twist1-positive CAFs, and Twist1 is necessary and sufficient for the trans-differentiation formation of CAFs." (PMID 30175384, 2018).